SOX2 (SRY-box transcription factor 2)
Diseases named in the same sentence as SOX2 in open-access papers (continued):
Sharing a sentence is not in itself a finding about the gene and the disease.
tumor (continued). "Finally, it should be stressed that comparisons of SOX2 expression between tumor cells and normal tissues may be misleading, because tumor cells arise from a small subset of cells in a tissue and the expression of SOX2 in this subset of cells may differ from that in the remainder of the tissue." (PMID 28388544, 2017). "GCSs-enriched spheres expressed higher levels of pluripotency markers: NANOG, POU5F1, SOX2 and CD133 as compared to the adherent tumor cells." (PMID 27934912, 2016). "The pluripotency factors, such as NANOG, SOX2, OCT4, and LIN28A, suggest a close relationship between tumor formation and the process of reprogramming mature cells to a more primitive type." (PMID 26910839, 2016). "SOX2 (red) and SALL4 (green) were co-expressed (appearing as orange) by cells within the tumor nests and the stroma, and the endothelium of the microvessels (red)." (PMID 27532037, 2016). "In CRC, SOX2 has previously been suggested to regulate epithelial-mesenchymal transition (EMT) and increased tumor migration and invasion." (PMID 27411517, 2016). "Beside ALDH1A1 and SOX2, other molecules such as DKK1 and NOTCH1 were notably upregulated in CSCs during tumor progression." (PMID 27292183, 2016). "Both SOX2 (brown) and SALL4 (brown) showed positive nuclear staining with increased expression especially toward the periphery of the tumor nests." (PMID 27532037, 2016). "Knocking down ZEB2 significantly suppressed the percentage of SP cells and DDP resistance by reducing the expression of tumor stemness factors including BMI1, SOX2, NANOG, and OCT4." (PMID 27589832, 2016). "Immunohistochemistry demonstrates tumor cells were positive for GFAP, OLIG2, SOX2, IDH1(R132H) and a MIB1 proliferation index of >30 %." (PMID 26817999, 2016). "Of the SOX2 positive tumors, 73.9 % had less than 50 % CDX2 positive tumor cells, and of these 32.6 % had less than 5 % positive cells." (PMID 27411517, 2016). "In addition, we used another RNA-seq dataset from 105 non-small cell lung cancer cell lines (NSCLC; including 4 lung SCC cell lines) and again analyzed the correlation between SOX2 and the reported SOX2-controlled genes in the NSCLC cell lines (no tumor-associated cells)." (PMID 26846300, 2016). "SOX2 (red) and OCT4 (green) were also co-localized (appearing as orange) to cells within the tumor nests and the stroma, and the endothelium of the microvessels." (PMID 27532037, 2016). "Epigenome-wide mapping of chromatin states in GBMs identified four core transcription factors, such as POU3F2 (also called OCT7, BRN2), SOX2, SALL2, and OLIG2, which are able to reprogram differentiated tumor cells into GSCs8." (PMID 27934912, 2016). "Subsequently, we performed triple immunofluorescent staining for SOX2, HIF-1α, and RNApII-S2P, and found a small number of tumor cells showing a SOX2+ HIF-1α+ RNApII-S2P-/low phenotype in the vicinity of necrotic areas." (PMID 26799577, 2016). "SOX2 expression is upregulated in LSCC, and therefore SOX2 is used as one of the tumor markers for LSCC." (PMID 28105432, 2016). "The expression of Oct4, Sox2, Gli1, CD44, CD133, p-AKT, and p-ERK was positively correlated with a more aggressive tumor phenotype and poorer overall prognosis." (PMID 26769843, 2016). "We observed significant correlation of FGFR1 expression with high tumor pN, pT stages, large tumor size, and increased expression of several biomarkers (ER, Ki67, P63, CG, SYN and SOX2)." (PMID 26673008, 2016). "4-HPR was able to decrease the expression CD133 and ABCG-2 surface antigens as well as Oct-4 and Sox-2 gene expression in BTICs and, suggesting that 4-HPR targets the BTIC tumor component." (PMID 27367907, 2016). "Several factors related with the CSC phenotype, such as ALDH1A1, SOX2, DKK1 and NOTCH1, were increasingly upregulated in the emerging CSC subpopulations during tumor progression." (PMID 27292183, 2016).
tumor (continued). "Compared to tumor sections prepared by control A2780 cells, the expression of NICD1, NANOG, OCT4 and SOX2 was significantly increased in those prepared by galectin-3 overexpressing A2780 cells." (PMID 27626163, 2016). "We confirmed higher expression of pluripotency transcription factors (NANOG, POU5F1, SOX2) and CD133 in cells forming tumor spheres." (PMID 27934912, 2016). "Here, we reexamined the role of SOX2 in PDAC cells, because inducible SOX2 overexpression in other tumor cell types inhibits growth." (PMID 27145457, 2016). "Here we demonstrate that growth-arrest-specific transcript 5 (GAS5), a known tumour suppressor and growth arrest-related lncRNA, is highly expressed and directly regulated by pluripotency factors OCT4 and SOX2 in hESCs." (PMID 27811843, 2016). "Hypoxic sites in tumors can produce CSC niches and induce stemness in tumor cells through hypoxia inducible factor 1 (HIF-1) and activation of transcription factors involved in reprogramming of iPSCs: Oct4, Sox2, Nanog and KLF4." (PMID 27898034, 2016). "These infiltrating tumor cells showed activation of EGFRvIII/STAT3 signaling and expression of stemness markers (Nestin and Sox2) in vivo." (PMID 25992628, 2015). "Akt/mTOR pathway was highly activated in CRPC and p-Akt was reported to target and stimulate the expression of tumorigenic factors like c-MYC, SOX2, OCT4 and eventually robust tumor growth." (PMID 26317998, 2015). "In multivariate analysis, residual tumor, Class III β-tubulin, and Sox2 remained as unfavorable independent prognostic variables for PFS (p = 0.002, 0.038, and 0.047, respectively)." (PMID 26198101, 2015). "We show that miRNA-148a is repressed by Oct4/Sox2 in a DNA methylation-dependent manner and this miRNA functions as an inhibitor of GBM cell stemness and tumor-initiating capacity." (PMID 27158195, 2015). "Expression of these transcription factors (POU3F2, Sox2, SALL2, and OLIG2) was found to be sufficient to recapitulate the epigenetic landscape and phenotype of the original tumor initiating cell population." (PMID 27158195, 2015). "We also found significant increases in FoxM1 and Sox2 expression in GBM cells after irradiation both in vitro and in vivo orthotopic tumor models." (PMID 26444992, 2015). "To further confirm the reduction of tumor was correlated with cancer stem cells, we used immunohistochemical staining to detect the p-STAT3 as well as CSCs markers OCT4, SOX2 and ALDH1." (PMID 26556875, 2015). "Previous studies have shown that over expressing SOX2 in ESCC cells promote proliferation and in vivo tumor growth." (PMID 26370982, 2015). "We have also found out that specific processes leading to induction of reprogramming to pluripotency (depicted by significant overexpression of NANOG, SOX2, and POU5F1) were triggered 20h after the treatment in the tumour cell population exposed to ROS." (PMID 26671576, 2015). "Knockdown of galectin-3 in lung adenocarcinomas decreased stemness-related genes like Oct4, Sox2, Nanog, and CD133, as well as the capability of tumor initiation in vitro and in vivo." (PMID 25669973, 2015). "To test the physiological significance of SOX2 induction following withdrawal ofmutant EGFR signaling, we first made use of mouse tumor models." (PMID 25686219, 2015). "Sox-2, Olig-2 and GFAP were present at high levels in proliferative cells and expressed in the invasive part of the tumor, and T121 staining confirmed suppression of RB (Sox-2, Sox-2/I, Olig-2, Olig-2/I, T121, T121/I and GFAP, GFAP/I)." (PMID 25431423, 2015).
tumor (continued). "We also found that the growth inhibitory effect of ICG-001 is correlated with the downregulated expression of the NPC CSC-like markers SOX2 and CD44, and the upregulated expression of the tumor suppressive microRNA-145 (miR-145)." (PMID 25897700, 2015). "SOX2 and CDX2 expression were crossed with clinicopathological and follow-up data to determine their impact on tumor behavior and outcome." (PMID 25300947, 2014). "In the present study we evaluated SOX2 expression in primary CRC, as well as in samples of corresponding liver metastasis, and correlated our findings to patient prognosis and molecular tumor characteristics." (PMID 25010701, 2014). "The BORIS-positive cells isolated using BORIS-molecular beacon, expressed higher telomerase hTERT, stem cell (NANOG, OCT4, SOX2) and cancer stem cell marker genes (CD44 and ALDH1) compared to the BORIS-negative tumor cells." (PMID 25279549, 2014). "In the present study, we used a more precise assay (ompare to Conventional immunohistochemical expression analysis), IHC in tissue arrays, and found that SOX2 was overexpressed in CRC tissues and was correlated with tumor grade." (PMID 24885288, 2014). "Expression of Tg and NIS was markedly decreased in the tumor tissue, while the stem cell markers (Oct4, Rex1, CD15, and Sox2), although detectable in normal thyroid, were greatly increased in the neoplastic tissues." (PMID 25076938, 2014). "Our results show that SOX2 and TP63 proteins are found in the nucleus of most tumour cells in HR-HPV+ve SCCC biopsies." (PMID 25531390, 2014). "The parental adherent monolayer HeLa cells scarcely expressed ALDH1 and SOX2, while stable ALDH1 and SOX2 expression was detected in tumor sphere HeLa cells." (PMID 24676900, 2014). "In that particular study, SOX2 down-regulation in the EC cell line NEC8, when established in vivo, induced tumor growth suppression in case of a limited tumor size." (PMID 24404135, 2014). "The aim of the present study was to evaluate expression of additional regulators belonging to the stem cell niche, OCT4, SOX2 and BMP7, as well as some microRNAs, reported to act as tumor suppressors or oncomiRs." (PMID 25340937, 2014). "Twenty-seven of these were only polyploid; 22 were polyploid and amplified, with CEP3: TERC/SOX2 FISH ratios that varied from 3:6–8, to 3–4:9–12 to 4:6–11 in the same tumor." (PMID 24410919, 2014). "As an example, the synergistic regulation of histone deacetylase 1 (HDAC1) by OCT4, SOX2 and NANOG plays important roles not only in the development of ESCs but also in the growth of tumor cells." (PMID 25171496, 2014). "To assess the correlation between the expression of TAM and CSC markers in human OSCCs, we stained the tumor sections from human tissue arrays for OSCC with antibodies for CD68, CD163, SOX2, ALDH1, and CD44 and compared them with normal oral mucosa samples." (PMID 24883329, 2014). "Previous reports have shown that TAMs contribute to tumor progression through secretion EGF and upregulation of the EGFR/Stat3/Sox-2 signaling pathway." (PMID 24312366, 2013). "AT13387 effectively reduced both the number and size of C666-1 tumor spheres with decreased expression of NPC CSC-like markers CD44 and SOX2." (PMID 24156782, 2013). "The results revealed that the expression levels of Oct4, Sox2, Klf4, c-Myc and Nanog in HCC specimens were signifcantly higher than those in the corresponding adjacent non-tumor tissues." (PMID 23599755, 2013). "In this study, we provided evidence showing that Sox2 induced autophagy through the up-regulation of ATG10 gene expression and cellular senescence, resulting in inhibition of tumor growth ex vivo and in vivo." (PMID 23451179, 2013). "The SOX2 and PIK3CA genes both reside on the long arm of chromosome 3 (3q26) and these genes were amplified in three HPV+ samples and one HPV- tumor." (PMID 23718828, 2013).
tumor (continued). "The identification of pluripotency factors such as SOX2, OCT4, KLF4 and LIN28A in human cancer suggests a close relationship between tumor formation and the process of reprogramming mature cells to a more primitive type." (PMID 23846349, 2013). "Immunohistochemical analysis of tumor xengrafts further confirmed that NANOG overexpression enhanced tumor development and increased expressions of cancer stemness protein-SOX2 and MUC1 in tumor xengrafts." (PMID 23662114, 2013). "Both “cancer stem-like” cells and tumor cells undergoing EMT are characterized by drug resistance, and are known to overexpress several transcription factors, including OCT4 and SOX2, that are involved in the control of cell pluripotency." (PMID 24125763, 2013). "Since NANOG knockdown suppressed mammosphere formation and reduced levels of SOX2 and MUC1 in tumor xengrafts, we next tried to determine if propagation of CD24−/lowCD44+ breast CSC subpopulation in MCF-7 cells is also regulated by NANOG." (PMID 23662114, 2013). "Sox2 in NSCLC have a higher expression, which is closely related to histological type and tumor size." (PMID 24229625, 2013). "To examine Sox2, ATG10 and ATG8b protein levels in tumor tissues, we conducted an immunofluorescence assay by confocal microscope using Sox2, ATG10 and ATG8b antibodies." (PMID 23451179, 2013). "After stimulation with various concentrations of BCE (62.5, 125, 250, 500 or 1,000 μg/ml) for 24 and 72 h, tumor cells were analyzed by qRT-PCR or western blot analyses for the expression of the stem cell genes NANOG, POU5F1 and SOX2, respectively." (PMID 23969837, 2013). "Consistent with immunohistochemical staining, SOX2 and OCT4 were localized in the nucleus of tumor cells, Nanog was localized in the cytoplasm of cancer cells and Nestin was found to be present in the cytoplasm of endothelial cells, respectively." (PMID 23424657, 2013). "We found that SOX2 is expressed at high level in SP/ALDHBr cells, and knockdown of SOX2 suppressed the expressions of ALDH1A1 and ABCG2, and suppressed tumor-initiation." (PMID 23967051, 2013). "The results suggested that Sox2 mRNA is upregulated in HCC tissue, compared with in the adjacent non-tumor tissue and is correlated with a large tumor size." (PMID 23599755, 2013). "In this study, we investigated the expression of Sox2 and Oct4 in 44 human NSCLC cancerous and their precancerous tissues and 21 benign human tumor tissues." (PMID 22837720, 2012). "We investigated Sox2 and Oct4 protein expression by IHC in 44 human NSCLC cancerous and precancerous tissues and 21 human benign tumor tissues." (PMID 22837720, 2012). "In cervical cancer, SC markers SOX2 and SMOOTHENED were recently shown to be overexpressed by nearly all the cells within tumour mass." (PMID 22880087, 2012). "We examined SOX2 expression by IHC of paraffin-embedded tumor tissues from 44 CRC patients and found that ∼20% of patients (9/44) stained strongly with the SOX2 antibody." (PMID 22912670, 2012). "CD133-positive cells, isolated from the tumor, expressed stem cell markers including nestin, CD133, Ki67, Sox2, EFNB1, EFNB2, EFNB3, Cav-1, Musashi, Nucleostemin, Notch 2, Notch 4, and Pax6." (PMID 22995409, 2012). "We examined histological phenotype of tumors of AFPC or NEC containing the composite tumor by evaluating immunohistochemical expressions of MUC2, MUC5AC, MUC6, CDX2, and SOX2." (PMID 22482081, 2012). "Through comprehensive characterization of the NPC spheroids, tumor lines and primary tumor, we have revealed that CD44 and SOX2 are potential CSC markers for NPC." (PMID 23285037, 2012). "From previous reports demonstrating that elevation of SOX2 can enable certain tumor cells to grow more rapidly, we postulated that, given enough time in the presence of elevated SOX2, a subpopulation of tumor cells could emerge which expressed exogenous SOX2 and proliferates rapidly." (PMID 22937156, 2012).
tumor (continued). "We then tested the expression levels of genes that correlate with “stemness,” namely Oct-4, Sox-2, and Nanog, in cancer cells from adherent culture systems, as well as CD133+ and CD133- cells from tumor spheres." (PMID 22643117, 2012). "Since it is understood that Twist1 and Sox2 regulate the metastatic ability of tumor cells and their involvement in stemness preservation, we analyzed the hUCBSC co-culture treated GSC for Sox2 and Twist1 expression." (PMID 22184289, 2011). "As evidenced by the significant increase in the expression of both Twist1 and Sox2 in the necrotic tumor areas, and their co-regulatory effect in siRNA transfectants, we next asked whether this expression is the co-regulatory mechanism necessitated by the interaction between Twist1 and Sox2." (PMID 22184289, 2011). "Second, placenta- and tumor-specific PLAC1 expression, which was down-regulated by SOX2 over-expression, was significantly up-regulated by SOX2 knockdown with Pre-miR-126 and siRNA in HSC43 cells." (PMID 21304604, 2011). "We investigated the co-regulatory role of Sox2 and Twist1 in GSC and their combinatorial effect on stemness maintenance and tumor progression." (PMID 22184289, 2011). "High expression of Twist1 and Sox2 was observed in the necrotic regions of U251 and 5310 GSC induced tumor, while hUCBSC-treated U251 and 5310 xenografts showed reduced or no expression of either Twist1 or Sox2 in individual experiments." (PMID 22184289, 2011). "Notably, SOX2 emerged as a key transcriptional difference, being highly enriched in Ivl:BRAFV600E tumours, relative to K5/K14:BRAFV600E tumours." (PMID 41507151, 2026). "IL-17RA overexpression significantly increased CSC marker expression, including cluster of differentiation 133 (CD133), leucine-rich repeat-containing G protein-coupled receptor 5 (LGR5), sex determining region Y-box 2 (SOX2), and enhanced tumor sphere formation and 5-FU resistance in SW620 cells." (PMID 41438576, 2026). "For example, SOX2 sustains tumor stemness to promote chemotherapy resistance, SOX4 modulates EMT and angiogenesis and SOX9 collaborates with EGFR/KRAS signaling pathways to drive tumor invasion." (PMID 41268614, 2026). "To confirm the safety of NILB-hiPSCs transplantation and rule out the possibility of tumor formation, we conducted staining for SOX2 and Ki67." (PMID 41362729, 2026). "In skin SCC specifically, SOX2 is not expressed in the interfollicular epidermis under homeostatic conditions, but marks tumor-initiating cells in mouse models of skin SCC and is required for maintaining their self-renewal and tumorigenic capacity." (PMID 41266112, 2026). "SOX2 levels did not correlate with the patient's age or tumour aggressiveness (tumour depth or diameter)." (PMID 41507151, 2026). "Although SOX2 is expressed in subpopulations of both human and mouse NC cells, its presence appears essential neither for tumor initiation nor for maintaining oncogenic transcriptional programs once NC is established." (PMID 41266112, 2026). "Collectively, these findings suggest that PP1γ may play an important role in tumor invasiveness and metastasis of ESCC through the PP1γ/YAP1/SOX2 axis." (PMID 40626009, 2025). "WT1 and FOXA1 silencing impaired the tumor-sphere forming ability of neurospheres treated with TMZ, decreased the spheroid frequency and reduced the mRNA expression of the stem markers NANOG, OCT4 and SOX2 (Fig. 4Gleft and right panels)." (PMID 40399259, 2025). "In addition, TAMs secrete high levels of IL-6 increasing stemness markers (i.e. SOX2, OCT3/4 and NANOG) and consequently CSCs expansion in breast cancer cells via STAT3 pathway supporting tumor cells migration and angiogenesis." (PMID 39981232, 2025). "Androgen deprivation therapy promotes the expansion of cancer stem cells (CSCs) by altering the tumor microenvironment and upregulating key stem cell markers, including OCT4, SOX2, NANOG, CD133, and CD44, driving tumor initiation, progression, and recurrence in PCa." (PMID 40722714, 2025).